MDM2 (MDM2 proto-oncogene)
Diseases named in the same sentence as MDM2 in open-access papers (continued):
Sharing a sentence is not in itself a finding about the gene and the disease.
chordoma (4 papers, 2009 to 2024). Chordomas are rare malignant tumors arising from embryonic remnants of the notochord in axial skeleton. "Genes central for module 2 (and thus probably important for functioning of chordomas in both clusters) were either responsible for cell division and DNA repair process (e.g. ATM, CHEK, BMI1, MDM2) or parts of inhibitors of apoptosis cascade (e.g. CASP2, CASP8, SIRT2)." (PMID 37434245, 2023). "This should be seen in the light of no reaction for D2-40 in chordomas and a corresponding lack of reaction for osteonectin, cox-2, mdm-2 and actin in extraskeletal myxoid chondrosarcomas." (PMID 19594492, 2009). "All five chordomas were negative for D2-40 and positive for mdm-2 and YKL-40." (PMID 19594492, 2009).
colon adenocarcinoma (4 papers, 2017 to 2025). "A previous study demonstrated that LINC00342 affects various cellular processes in colon adenocarcinoma (COAD) both in vivo and in vitro by modulating miR-545-5p/MDM2 expression." (PMID 34954694, 2021). "Immunofluorescence staining has revealed that PXR protein level is ubiquitously higher in human colon adenocarcinoma tissues than that in adjacent non-tumor tissues, whereas MDM2 protein expression has the opposite trend with PXR in tumor tissue vs. that in adjacent non-tumor tissues." (PMID 35372071, 2022).
diabetic kidney disease (4 papers, 2023 to 2025). Progressive kidney disorder caused by vascular damage to the glomerular capillaries, in patients with diabetes mellitus. "A recent study demonstrated that MDM2 expression is dramatically attenuated in patients with diabetic nephropathy and in vitro or in vivo experiments." (PMID 40421968, 2025). "MDM2 is also significantly downregulated in patients with common diabetic nephropathy." (PMID 37632105, 2023). "Conversely, MDM2, an E3 ubiquitin ligase that modulates JAK–STAT and PI3K–Akt signaling and plays a protective role in diabetic kidney disease through NRF-2 regulation, was significantly downregulated in diabetic dogs, with no observed improvement detected after astaxanthin supplementation." (PMID 40333882, 2025).
epilepsy (4 papers, 2019 to 2022). A brain disorder characterized by episodes of abnormally increased neuronal discharge resulting in transient episodes of sensory or motor neurological dysfunction, or psychic dysfunction. "Therefore, we provide a new paradigm for the development of therapeutic strategies for epilepsy and neurological diseases associated with deregulation of NF2 and Mdm2." (PMID 33414453, 2021).
esophageal adenocarcinoma (4 papers, 2003 to 2025). A malignant tumor with glandular differentiation arising predominantly from Barrett mucosa in the lower third of the esophagus. "Among the 1114 cases with an adenocarcinoma of the esophagus, gastroesophageal junction, or stomach documented in the cBioPortal database (search date 17 September 2023), 72 (6.5%) cases harbored an MDM2 amplification and only 8 (0.7%) a mutation." (PMID 37821635, 2023). "Recently, a study of esophageal adenocarcinoma linked MDM2 amplification to chromothripsis, likely mirroring the results reported here in GBM." (PMID 26328271, 2015). "Further investigations using MDM2-amplified esophageal adenocarcinoma cell lines are needed to evaluate their response to existing MEK inhibitors." (PMID 41299419, 2025). "Our results encourage the investigation of CTL2 as a possible therapeutic target for patients with MDM2-amplified esophageal adenocarcinoma." (PMID 41299419, 2025). "Patients with esophageal adenocarcinoma with MDM2 amplification showed a poor treatment response followed by neoadjuvant therapy in a retrospective trial, resulting in a significantly worse progression-free survival of these patients." (PMID 41299419, 2025). "In esophageal adenocarcinoma, a shorter progression-free survival was reported for patients with MDM2-amplified tumors." (PMID 41299419, 2025). "Surely, other elements like mRNAs, phosphorylation status, or the cellular tumor microenvironment influence the tumorigenesis of MDM2-amplified esophageal adenocarcinomas." (PMID 41299419, 2025). "We screened 656 patients with esophageal adenocarcinoma for their MDM2-amplification status using Fluorescence in situ Hybridization." (PMID 41299419, 2025). "We hypothesize that patients with MDM2-amplified esophageal adenocarcinoma would potentially benefit from this treatment." (PMID 41299419, 2025). "This suggests that evading immune destruction, one of the hallmarks of cancer, may be a key factor in the pathogenesis of MDM2-amplified esophageal adenocarcinomas." (PMID 41299419, 2025). "MDM2 amplification also occurs in esophageal adenocarcinoma in approximately 6% of all patients." (PMID 41299419, 2025). "We identified several potential therapeutic targets that could serve as additional therapy options, together with MDM2 inhibitors, for patients with MDM2-amplified esophageal adenocarcinoma." (PMID 41299419, 2025). "Thirty-six proteins showed an overexpression in MDM2-amplified esophageal adenocarcinomas." (PMID 41299419, 2025). "Here, potential additional treatment options for patients with MDM2-amplified esophageal adenocarcinoma could be described, for example, the inhibition of CTL2 or MEK with Trametinib, which is currently under investigation as an antitumoral treatment agent." (PMID 41299419, 2025). "However, this pathway seems to be downregulated in MDM2-amplified esophageal adenocarcinomas." (PMID 41299419, 2025). "This could be a possible therapeutic target for MDM2-amplified esophageal adenocarcinomas." (PMID 41299419, 2025). "Moreover, patients with MDM2-amplified esophageal adenocarcinoma could be eligible for inhibitors of the tryptophan metabolism, like IDO1 enzyme inhibitors." (PMID 41299419, 2025). "The aim of this study was to investigate the differences between esophageal adenocarcinomas with and without MDM2 amplification on the proteome level." (PMID 41299419, 2025). "This study investigated the proteome of MDM2-amplified esophageal adenocarcinomas compared with non-amplified tumors." (PMID 41299419, 2025).
esophageal adenocarcinoma (continued). "Therefore, we aimed to characterize the proteome of MDM2-amplified esophageal adenocarcinomas in comparison to non-amplified tumors, identifying altered pathways as potential additional therapeutic targets." (PMID 41299419, 2025).
Hodgkin disease (4 papers, 2007 to 2018).
Infertility (4 papers, 2016 to 2024). "Besides, research has shown the importance of MDM2 protein in the impairment of oocyte maturation in the mice models as mice with MDM2 deficiency in GCs were infertile owing to the loss of oocyte maturation, ovulation, and fertilization." (PMID 37468508, 2023). "More importantly, there is positive correlation of MDM2 and Sf1 levels in human GCs with the outcome of oocyte maturation and fertilization in patients undergoing infertility treatment." (PMID 37468508, 2023).
invasive ductal breast carcinoma (4 papers, 2014 to 2019). The most common type of invasive breast carcinoma, accounting for approximately 70% of breast carcinomas. "In spite of shorter disease-free survival of invasive ductal breast carcinoma patients with MDM2-expressing tumors, these tumors were significantly smaller and fewer patients with the MDM2-expressing tumors presented with LN metastases." (PMID 26416355, 2015). "Also, MDM2 overexpression in MCF-7 (estrogen receptor positive, Her2-negative) and MDA-MB-231 (triple-negative) cell lines promotes invasion and metastasis in invasive ductal breast carcinoma by upregulating matrix metalloproteinase-9." (PMID 25278993, 2014).
Li-Fraumeni syndrome (4 papers, 2008 to 2013).
ossifying fibroma (4 papers, 2017 to 2023). A bone benign neoplasm that is located_in the mouth and results_in an overgrowth of gingival tissue due to irritation or trauma. "MDM2 amplification has been reported in craniofacial BFOLs, especifically in juvenile ossifying fibromas and ossifying fibromas." (PMID 37232789, 2023). "Juvenile ossifying fibromas have the potential to evolve into a giant-cell–rich variant of high-grade OS and are shown to be associated with RASAL1 amplification or RASAL1/MDM2 coamplification." (PMID 29244987, 2017).
osteoporosis (4 papers, 2020 to 2025). A condition of reduced bone mass, with decreased cortical thickness and a decrease in the number and size of the trabeculae of cancellous bone (but normal chemical composition), resulting in increased fracture incidence. "Finally, we assessed the regenerative effects of MDM2‐PROTAC after general administration using ovariectomy (OVX)‐induced osteoporosis model." (PMID 40125646, 2025).
pancreatic ductal adenocarcinoma (4 papers, 2011 to 2021). An infiltrating adenocarcinoma that arises from the epithelial cells of the pancreas. "Earlier we had shown that the MDM2 inhibitor (MI-219) belonging to the spiro-oxindole family can synergistically enhance the efficacy of platinum chemotherapeutics leading to 50% tumor free survival in a genetically complex pancreatic ductal adenocarcinoma (PDAC) xenograft model." (PMID 21623005, 2011). "Moreover, MDM2 inhibitor (nutlin-3) delayed DNA repair of DSB in pancreatic ductal adenocarcinoma (PDAC model), suggesting that MDM2 inhibitors block MDM2 activities needed for effective DNA repair." (PMID 34572735, 2021).
Parkinson disease (4 papers, 2008 to 2023). A progressive degenerative disorder of the central nervous system characterized by loss of dopamine producing neurons in the substantia nigra and the presence of Lewy bodies in the substantia nigra and locus coeruleus. "However, its connection to several query genes (Tbp and Mapt) and to several proteins functionally related to the query set (Mdm2, Fyn, Psen1, Apoe, Uchl1, and Dbh) in mouseNET suggests its potential role in Parkinson's disease." (PMID 18818725, 2008). "Well known examples are deregulation of the E3s BRCA1, Mdm2, VHL and Skp2 in various cancers, and Parkin in Parkinson's disease." (PMID 18213395, 2008).
prostate adenocarcinoma (4 papers, 2009 to 2025).
pulmonary hypertension (4 papers, 2022 to 2025). Increased pressure within the pulmonary circulation due to lung or heart disorder. "Recently, it has been shown that MDM2 can mediate the ubiquitination of ACE2 at position K788 and that MDM2 regulation is disrupted in patients suffering from pulmonary arterial hypertension." (PMID 37632105, 2023). "Serdemetan, an MDM2 inhibitor, mitigates experimental pulmonary hypertension (PH) in mice, partially through the inhibition of MDM2-mediated ubiquitination of angiotensin-converting enzyme 2 (ACE2) and thus rectified ACE2 expression." (PMID 35301297, 2022). "First, the mechanistic roles of identified hub genes, including VEGFA, MDM2, and PTGS2, must be functionally assessed using both in vitro and in vivo pulmonary hypertension models." (PMID 41137320, 2025). "Inhibition of MDM2 increases ACE2 levels in the lung tissues of mice and alleviates pulmonary hypertension of mice." (PMID 37608279, 2023).
spindle cell lipoma (4 papers, 2023 to 2025). A benign circumscribed tumor composed of spindled cells, adipocytes, and collagen bundles. "For instance, the distinction between atypical lipomatous tumors and spindle cell lipoma often requires the confirmation of MDM2 and CDK4 amplification." (PMID 40870476, 2025). "Therefore, when distinguishing from atypical spindle cell lipoma-like tumors, FISH detection of MDM2 amplification becomes the gold standard for diagnosing DDLPS." (PMID 41450911, 2025).
stomach tumor (4 papers, 2021 to 2023). "To investigate the effect of GLA on the mRNA stability of MDM2 and RNF6 in gastric tumor cells, we used actinomycin D, a transcription inhibitor widely used to inhibit the synthesis of new mRNA in the assessment of mRNA decay." (PMID 35814430, 2022).
adenoma (3 papers, 2008 to 2025). A neoplasm arising from the epithelium. "Immunohistochemical findings showed nuclear positivity for a murine double minute 2 (MDM2) and cyclin-dependent kinase 4 (CDK4) and negativity for pleomorphic adenoma gene 1 (PLAG1)." (PMID 39109289, 2024).
adrenocortical carcinoma (3 papers, 2022 to 2025).